TOMM22P4 (TOMM22 pseudogene 4)
Gene: Processed pseudogene on chromosome 4 (162,521,682 to 162,522,041, forward strand). Ensembl gene ENSG00000248396.
Diseases named in the same sentence as TOMM22P4 in open-access papers:
TOMM22P4 is named in the same sentence as 1 disease in open-access papers, as found by Europe PMC text mining. Sharing a sentence is not in itself a finding about the gene and the disease.
cancer (1 paper, 2023). A tumor composed of atypical neoplastic, often pleomorphic cells that invade other tissues.